ABAT (4-aminobutyrate aminotransferase)
Description:
Catalyzes the conversion of gamma-aminobutyrate and L-beta-aminoisobutyrate to succinate semialdehyde and methylmalonate semialdehyde, respectively. Can also convert delta-aminovalerate and beta-alanine (By similarity).
Synonyms: GABA-AT; GABA-T; GABAT; NPD009
Tractability: Small molecule: an approved drug acts on it; a high-quality ligand is known; it belongs to a druggable protein family. PROTAC: its protein half-life has been measured; a small molecule that binds it is known.
Target class: Enzyme; Transferase
Gene: Protein-coding gene on chromosome 16 (8,674,596 to 8,784,575, forward strand). Ensembl gene ENSG00000183044.
Subcellular location: Mitochondrion matrix
Subcellular location (Human Protein Atlas): Mitochondria
Pathways (Reactome):
Neuronal System: Degradation of GABA
Gene Ontology:
Molecular function: 4-aminobutyrate:2-oxoglutarate transaminase activity; pyridoxal phosphate binding; (S)-3-amino-2-methylpropionate transaminase activity; succinate-semialdehyde dehydrogenase binding
Biological process: gamma-aminobutyrate shunt; gamma-aminobutyric acid catabolic process; nervous system process; cerebellum development; copulation; exploration behavior; locomotory behavior; negative regulation of blood pressure; negative regulation of dopamine secretion; negative regulation of gamma-aminobutyric acid secretion; positive regulation of aspartate secretion; positive regulation of dopamine metabolic process; positive regulation of heat generation; positive regulation of inhibitory postsynaptic potential; positive regulation of insulin secretion; positive regulation of prolactin secretion; positive regulation of uterine smooth muscle contraction; response to cocaine; response to ethanol; response to hypoxia; response to iron ion; response to nicotine; response to xenobiotic stimulus
Cellular component: 4-aminobutyrate transaminase complex; mitochondrion; mitochondrial matrix
Genetic constraint (gnomAD): Loss-of-function variants: 45 observed, 66.22 expected, observed/expected ratio (o/e) 0.68, 90% interval 0.53 to 0.87. The upper end of that interval is the gene's LOEUF score, 0.87, which puts it in group 3 of 6, group 1 being the genes least tolerant of losing a copy. Missense variants: 633 observed, 687.08 expected, observed/expected ratio (o/e) 0.92, 90% interval 0.86 to 0.98. Synonymous variants: 297 observed, 263.14 expected, observed/expected ratio (o/e) 1.13, 90% interval 1.03 to 1.24.
Gene-disease validity (ClinGen):
ClinGen rates the evidence that ABAT causes each of these diseases.
genetic developmental and epileptic encephalopathy (autosomal recessive): Moderate. A complex neurodevelopmental disorder characterized by a range of developmental delays and epileptic encephalopathy phenotypes.
Homologues: Orthologues: chimpanzee ABAT (99% identical), macaque ABAT (98% identical), guinea pig ABAT (94% identical), rabbit ABAT (94% identical), dog ABAT (93% identical), rat Abat (92% identical), mouse Abat (91% identical), pig ABAT (89% identical), tropical clawed frog abat (83% identical), zebrafish abat (70% identical), Drosophila melanogaster Gabat (51% identical), Caenorhabditis elegans gta-1 (45% identical). Paralogues in human: ETNPPL (21% identical), AGXT2 (21% identical), OAT (20% identical), PHYKPL (19% identical).
Diseases named in the same sentence as ABAT in open-access papers:
ABAT is named in the same sentence as 104 diseases in open-access papers, as found by Europe PMC text mining. Sharing a sentence is not in itself a finding about the gene and the disease. The quoted sentences say what the papers report.
epilepsy (23 papers, 2014 to 2026). A brain disorder characterized by episodes of abnormally increased neuronal discharge resulting in transient episodes of sensory or motor neurological dysfunction, or psychic dysfunction. "The defect of ABAT is associated with severe neurological disorders, such as early onset encephalopathy and epilepsy." (PMID 35216295, 2022). "ABAT deficiency phenotypes include psychomotor retardation, hypotension, hyperreflexia, lethargy, refractory epilepsy, and abnormal EEG." (PMID 34539973, 2021). "Also, It was reported that the activity of ABAT was correlated to certain neuropsychiatric disorders such as epilepsy and Alzheimer's disease." (PMID 25153931, 2014).
breast cancer (18 papers, 2012 to 2023). A primary or metastatic malignant neoplasm involving the breast. "Estrogen-receptor positive (ER+) breast cancers express highly upregulated levels of ABAT transcripts and its encoded protein, and have a more favorable patient prognosis, than low-ABAT-expressing hormone-insensitive breast cancers." (PMID 33187258, 2020). "In the present study, low ABAT expression is significantly associated with basal-like breast cancer aggressiveness by activating gamma-aminobutyric acid (GABA) signaling." (PMID 32093682, 2020). "For breast cancer, the loss of ABAT expression could promote the potency of tumorigenesis and metastasis, which could be a predictive biomarker for endocrine therapy resistance." (PMID 36176391, 2022). "For example, ABAT is down-regulated in clear cell renal carcinoma tissues and basal-like breast cancer tissues, and over-expression of ABAT suppresses tumor cell growth." (PMID 35216295, 2022). "ABAT was related to the prognosis of patients with liver cancer, pancreatic cancer, and breast cancer." (PMID 34539973, 2021). "The low expression of ABAT in basal cell-like breast cancer (BLBC) promoted the increase of GABA, thereby enabling the development and metastasis of cancer cells by activating the Ca2 + -NFAT1 axis." (PMID 34539973, 2021). "In addition, a decreased expression of the aminobutyrate aminotransferase (ABAT), highlighted in GABAergic signaling, is associated with increased intracellular [Ca2+], leading to an increased Ca2+-sensing nuclear translocation associated with aggressive breast cancer." (PMID 32612536, 2020). "Importantly, decreased expression of ABAT gene hallmarked ER-positive inflammatory breast cancer and endocrine therapy resistance in advanced disease." (PMID 36163180, 2022). "Besides, alterations in the expression levels of ABAT have been reported in the promotion of breast cancer." (PMID 33962648, 2021). "ABAT was also identified as a biomarker for endocrine-responsiveness breast cancer patients." (PMID 33962648, 2021). "In this context, an SRM-based study by Pavlou and collaborators in 2014 suggested that higher levels of 4-aminobutyrate aminotransferase (ABAT) could be related to better prognosis in breast cancer patients, specifically those who are ER positive, tamoxifen treated, and with grade II staging." (PMID 28265552, 2017). "In breast cancer patient datasets (TCGA, Cell 2015 and METABRIC), expression of ABAT was negatively correlated while expression of GABRE was positively correlated with ALDH1A3 expression, consistent with the MDA-MB-231 data." (PMID 34989902, 2022). "Of these, six genes (ABAT, DEPDC1, KIF2C, SMAD4A, TAF1D, and TUBB6) have been reported to be directly relevant to cancer mechanisms, such as mammary tumor progression (P = 0.046)." (PMID 23185353, 2012). "In estrogen receptor-positive (ER+) and negative (ER−) breast cancer, low expression of ABAT gene is found to be related to poor prognosis." (PMID 36163180, 2022). "In breast cancer, ABAT protein and mRNA expression showed a strong negative correlation with beta-alanine abundance." (PMID 36163180, 2022).
Anxiety (7 papers, 2019 to 2025). Intense feelings of nervousness, tension, or panic often arise in response to interpersonal stresses. "It is linked to the ABAT gene, which is also associated with the number of separation anxiety symptoms in similar magnitude and direction of effects." (PMID 38577817, 2024).
pancreatic cancer (5 papers, 2019 to 2023). "Model 3 primarily includes CARNS1, CNDP1, GATM, and ABAT, which are mainly distributed in tumors, particularly pancreatic cancer and breast cancer." (PMID 36914737, 2023). "ABAT expression is downregulated in several types of cancer, including renal carcinoma, breast cancer, and pancreatic cancer." (PMID 35847853, 2022). "The analytic results demonstrated that 7 upregulated (MMP9, CXCL8, ACTB, ITGB1, STAT1, TOP2A and CDK1) and 2 downregulated (GNMT and ABAT) hub genes may act as the key genes in pancreatic cancer." (PMID 31061236, 2019).
autism (4 papers, 2009 to 2020). Persistent deficits in social interaction and communication and interaction as well as a markedly restricted repertoire of activity and interest as well as repetitive patterns of behavior. "Single nucleotide variants in the ABAT gene, probably disrupting its protein function, may have a link to autism." (PMID 28771244, 2018). "Genes associated with disease such as MMRN1 (familial parkinsonism), ABAT (autism), and MAP6 (depression and schizophrenia-like symptoms) were also upregulated (for gene functions and references see Suppl." (PMID 23203475, 2013).
clear cell renal carcinoma (4 papers, 2020 to 2022). A malignant epithelial neoplasm of the kidney characterized by the presence of lipid-containing clear cells within a vascular network. "Recently, high ABAT transcript levels were found to correlate with positive patient outcome in clear cell renal carcinoma, and to decrease cell proliferation and migration while increasing cell death in a kidney cancer cell line model." (PMID 33187258, 2020). "The paired analysis showed that ABAT mRNA levels were significantly decreased in renal clear cell carcinoma tissue (p < 0.0001)." (PMID 32093682, 2020). "In renal clear cell carcinoma, low-expressed ABAT promoted tumor development by boosting cancer cells' metabolism, which the transcription factor HNF4A may regulate." (PMID 34539973, 2021).
myelodysplastic syndrome (4 papers, 2020 to 2022). A clonal hematopoietic disorder characterized by dysplasia and ineffective hematopoiesis in one or more of the hematopoietic cell lines. "High levels of ABAT methylation are correlated with poor patient survival in myelodysplastic syndrome." (PMID 33187258, 2020).
colorectal cancer (3 papers, 2023 to 2025). A primary or metastatic malignant neoplasm that affects the colon or rectum. "Using this system, they were able to identify GABAergic properties and the role of the GABA catabolism enzyme ABAT in colorectal cancer cell invasion, suggesting potential targets for drug development." (PMID 39101627, 2024). "The present study identified six hub targets—GOT1, CYP2C9, CYP34, CYP1A2, CA2, and ABAT—that are involved in five core pathways related to HQD’s effects on malignant progression in colorectal cancer liver metastases, integrating transcriptomic and metabolomic analyses." (PMID 40732339, 2025). "Inhibiting the synthesis of α-aminobutyric acid metabolism, using 4-aminobutyrate aminotransferase (ABAT), has been shown to reduce the proliferation and migration of colorectal cancer cells." (PMID 37233659, 2023).
lung carcinoma (3 papers, 2020 to 2025). "ABAT expression is also associated with the pathological types of lung cancer, exhibiting higher levels in lung squamous cell carcinoma compared to lung adenocarcinoma." (PMID 39972344, 2025). "Our findings indicate that lung cancer cells can activate the NF-κB pathway via the FOXA2/ABAT/GABA axis, thereby facilitating brain metastasis." (PMID 39972344, 2025). "In our analysis, we found that ABAT expression varied according to the pathological type of lung cancer." (PMID 39972344, 2025). "In total, in our study, we confirmed the role of ABAT/GABA axis in lung cancer brain metastasis and emphasis its ability to activate the NF-κB signaling pathway." (PMID 39972344, 2025). "We speculate that ABAT may be a key molecule involved in altering GABA during lung cancer brain metastasis." (PMID 39972344, 2025). "Because LMD samples from pediatric patient CSF were not readily available, we analyzed ABAT and ALDH5A1 expression in LMD samples from the CSF of patients with breast and lung cancer as a surrogate." (PMID 34192534, 2021).
mtDNA depletion syndrome (3 papers, 2021 to 2024). "ABAT, a key enzyme responsible for catabolism of principal inhibitory neurotransmitter γ-aminobutyric acid (GABA), exhibited the connection between GABA metabolism and nucleoside metabolism and played a key role in developing neurometabolic disorders such as mtDNA depletion syndrome." (PMID 36970281, 2023).
breast tumor (2 papers, 2022 to 2023). "In both patient groups, low ABAT expression in the primary breast tumor was significantly and strongly associated with increased risk of brain metastasis, while GABRE was not." (PMID 34989902, 2022). "We further confirmed the association of ABAT or GABRE expression with high ALDH1A3 in two independent datasets of primary breast tumors that later developed distal metastasis (GSE2034 and GSE12276)." (PMID 34989902, 2022). "Furthermore, when primary breast tumors had low ABAT expression, there was a higher risk for lung-specific metastasis and all distal sites excluding brain, but GABRE expression did not impact the risk of distant metastasis." (PMID 34989902, 2022).
CNS cancers (2 papers, 2024 to 2025). "Decreased ABAT gene expression, including due to hypermethylation, was shown to be associated with aggressive tumor behavior, resistance to adjuvant chemotherapy, and poor prognosis in some primary non-CNS cancers, such as breast, liver and adrenocortical carcinomas." (PMID 40575267, 2025). "Subsequent IHC staining revealed the expression of PDE8B, ABAT, and ADCY2 proteins in glioma WHO grades II-IV." (PMID 38989284, 2024). "Consistent with the changes in expression, patients with higher expression of LDHA, MIF, NAMPT, PGK1, SAT1, and PLOD2, and lower expression of ALDOC, ABAT, ADCY2, GALNT13, and PDE8B showed poorer survival rates in all glioma samples." (PMID 38989284, 2024). "The protein expression of PDE8B, ABAT, and ADCY2 decreased in glioma grade IV compared with glioma grades III and II." (PMID 38989284, 2024). "Similar to the TCGA datasets, all 11 genes exhibited WHO grade-dependent expression in glioma samples, with 6 upregulated (LDHA, MIF, NAMPT, PGK1, SAT1, and PLOD2) and 5 downregulated genes (ALDOC, ABAT, ADCY2, GALNT13, and PDE8B)." (PMID 38989284, 2024). "Regarding the primary-recurrent-secondary (PRS) type, ALDOC and ABAT exhibited decreased expression, while MIF and PGK1 showed increased expression in recurrent and secondary glioma groups." (PMID 38989284, 2024). "The expression of PDE8B, ABAT, and ADCY2 proteins decreased with increasing glioma WHO grade." (PMID 38989284, 2024).
experimental autoimmune encephalomyelitis (2 papers, 2015 to 2022). An autoimmune demyelinating disease of the central nervous system that is produced experimentally in animals by the injection of homogenized brain or spinal cord in Freund's adjuvant. "Accordingly, ablation of ABAT activity in T cells protects against experimental autoimmune encephalomyelitis (EAE) progression." (PMID 36192601, 2022).
glioblastoma (2 papers, 2020 to 2022). The most malignant astrocytic tumor (WHO grade IV). "Additionally, low levels of ABAT transcripts are associated with poor patient survival in mesenchymal glioblastoma as well as progression, recurrence, and reduced patient survival time in hepatocellular carcinoma (HCC)." (PMID 33187258, 2020). "In other cancers, reversal of transcriptional silencing by demethylating agents in a glioblastoma cell line increases ABAT transcript expression." (PMID 33187258, 2020). "Using the TTD database, we discovered that EGFR, ABAT, and PDGFRA are strongly associated with AQP4 expression in the glioblastoma (GBM) classification, and these factors could be the potential AQP4-related immunotherapy targets." (PMID 36523816, 2022).
hepatocellular carcinoma (2 papers, 2020). A malignant tumor that arises from hepatocytes. "This is in keeping with the correlation of low ABAT transcript expression with both an increased risk of metastasis in triple-negative breast cancer tumors and an increased expression of a “metastasis gene signature” in hepatocellular carcinoma." (PMID 33187258, 2020). "ABAT and ALDH6A1 are proved to be hub genes in association with metastasis risk and prognosis in hepatocellular carcinoma (HCC)." (PMID 32093682, 2020).
hepatoid adenocarcinoma (2 papers, 2017 to 2020). An adenocarcinoma with morphologic characteristics similar to hepatocellular carcinoma, arising from an anatomic site other than the liver. "In fact, ABAT protein is a highly sensitive biomarker for the identification of HCC and hepatoid adenocarcinomas." (PMID 33187258, 2020).
inflammatory breast carcinoma (2 papers, 2020 to 2021). An advanced, invasive breast adenocarcinoma characterized by the presence of distinct changes in the overlying skin. "This gene expression is downregulated in inflammatory breast cancer and low expression of ABAT is correlated with a poor tamoxifen treatment outcome." (PMID 34172056, 2021). "Conversely, the downregulation of ABAT promotes the progression of BLBC and resistance to endocrine therapy of inflammatory breast cancer." (PMID 33133125, 2020).
liver cancer (2 papers, 2021 to 2023). An epithelial or non-epithelial malignant neoplasm that arises from the liver. "Gamma-aminobutyrate aminotransferase (ABAT) was down-regulated in liver cancer tissue and cell levels, and low expression of ABAT was associated with poor prognosis in liver cancer." (PMID 36969015, 2023).
lung squamous cell carcinoma (2 papers, 2025). "A high intra-tumoral GAD1 expression is associated with a poorer prognosis, whereas the expression of GABA transaminase (4-aminobutyrate aminotransferase, or ABAT), which metabolizes GABA, is reduced in lung squamous cell carcinoma and colon adenocarcinoma." (PMID 40722337, 2025).
renal carcinoma (2 papers, 2020 to 2022). A carcinoma arising from the epithelium of the renal parenchyma or the renal pelvis. "In order to understand the mechanism of overexpressing ABAT or ALDH6A1 in renal cancer cells, database analysis shows that ABAT and ALDH6A1 are mainly involved in oncologic metabolism." (PMID 32093682, 2020). "By measuring the lactic acid production and NADP/NADPH ratio of renal cancer cells, the results showed that after ABAT or ALDH6A1 overexpression, oncologic metabolism was impaired." (PMID 32093682, 2020). "Overexpression of ABAT or ALDH6A1 reduced cell proliferation and migration and impaired oncologic metabolism of renal cancer cells." (PMID 32093682, 2020).
renal cell carcinoma (2 papers, 2020). "Moreover, ABAT has been identified as a prognostic factor for renal cell carcinoma and hepatic adenocarcinoma." (PMID 33133125, 2020). "Based on the pan-cancer analysis, both ABAT and ALDH6A1 were significantly down-expressed in three types of renal cell carcinomas, KIRC, kidney renal papillary cell carcinoma (KIRP), and kidney chromophobe (KICH)." (PMID 32093682, 2020).
triple-negative breast carcinoma (2 papers, 2020 to 2023). An invasive breast carcinoma which is negative for expression of estrogen receptor (ER), progesterone receptor (PR), and human epidermal growth factor receptor 2 (HER2). "Notably, triple-negative breast cancer has relatively low levels of ABAT transcripts and protein, and a very poor patient prognosis, with overexpression of ABAT reducing migration and invasiveness in triple-negative cell lines." (PMID 33187258, 2020).
basal-like breast carcinoma (1 paper, 2021). "The recent investigations on Basal-like breast cancer (BLBC), the most aggressive subtype of this cancer, have documented the expression of ABAT was considerably decreased in this cancer." (PMID 33962648, 2021).